MEIS1 (Meis homeobox 1)
Diseases named in the same sentence as MEIS1 in open-access papers (continued):
Sharing a sentence is not in itself a finding about the gene and the disease.
Bradycardia (1 paper, 2016). A slower than normal heart rate (in adults, slower than 60 beats per minute). "Here, we demonstrated that Meis1 inactivation results at adult stages in a persistent and spontaneous bradycardia, blocks of conduction and severe sinus arrests independently of any cardiac malformation." (PMID 26857994, 2016).
carcinomas in situ (1 paper, 2014). "Specifically, both RNA sequencing and RT-PCR analysis indicated that Meis1 expression is successively increased from papillomas to carcinomas in situ to metastatic carcinomas." (PMID 25013928, 2014). "In both carcinomas in situ and metastatic carcinomas, we observed that Meis1-EGFP was co-expressed with the epithelial basal marker K14, but not with the mesenchymal marker vimentin." (PMID 25013928, 2014). "We next investigated Meis1 expression in chemically induced papillomas, carcinomas in situ, and metastatic carcinomas of Meis1-EGFP mice by immunofluorescence." (PMID 25013928, 2014). "In carcinomas in situ, we found that Meis1-EGFP was co-expressed with K14." (PMID 25013928, 2014).
diabetic nephropathy (1 paper, 2012). "In this report we used Meis1-GFP transgenic mice to purify mesangial cells from normal mice and from db/db mice, which suffer diabetic nephropathy." (PMID 22839765, 2012).
ganglioglioma (1 paper, 2023). A well differentiated, slow growing neuroepithelial neoplasm composed of neoplastic, mature ganglion cells and neoplastic glial cells. "PAX6, MEIS1, and TCF7L2 concentrations as well as SCENIC-calculated regulon scores correlated strongly with ganglioglioma neoplastic cell stemness by CellRank/CytoTRACE pseudotime or SCENT signaling entropy rate." (PMID 36966348, 2023).
HCMV infection (1 paper, 2022). "During HCMV infection, numerous HOX genes, including MEIS1, are differentially expressed." (PMID 35628509, 2022).
heart failure (1 paper, 2025). Inability of the heart to pump blood at an adequate rate to meet tissue metabolic requirements. "It is therefore evident that regulating Meis1 would provide potential therapeutic avenues in many pathological conditions like heart failure, cancer, and developmental disorders." (PMID 39851553, 2025).
Hodgkins lymphoma (1 paper, 2021). A heterogeneous group of malignant lymphoid neoplasms of B-cell origin characterized histologically by the presence of Hodgkin and Reed-Sternberg (HRS) cells in the vast majority of cases. "Subsequent expression analysis of TALE homeobox genes in public datasets of Hodgkin lymphoma (HL) patients revealed overexpression of IRX3, IRX4, MEIS1, MEIS3, PBX1, PBX4 and TGIF1." (PMID 33539429, 2021).
itch (1 paper, 2022). "Furthermore, Meis1 mutation impairs the behavioral response to static touch, light mechanical pain and chemical itch." (PMID 35875660, 2022).
kidney cancer (1 paper, 2024). Primary or metastatic malignant neoplasm involving the kidney. "MEIS1, along with VEGFR-2, was significantly downregulated in early-stage kidney cancer tissues compared to adjacent normal tissues." (PMID 38347632, 2024).
metastatic carcinoma (1 paper, 2014). A carcinoma which has spread from the original site of growth to another anatomic site. "In metastatic carcinomas, Meis1-EGFP was expressed throughout the metastatic carcinoma." (PMID 25013928, 2014).
multiple sclerosis (1 paper, 2019). A progressive autoimmune disorder affecting the central nervous system resulting in demyelination. "Although, there is no direct association of MEIS1 with multiple sclerosis, the rs2300478 polymorphism of MEIS1 is proven to contribute to neurological diseases." (PMID 31484947, 2019).
pancreatic cancer (1 paper, 2020). "MEIS1 protein may alter mitochondrial activity and it is associated with metabolic pathways in pancreatic cancer (PaC)." (PMID 33402862, 2020).
papilloma (1 paper, 2014). A benign epithelial neoplasm that projects above the surrounding epithelial surface and consists of villous or arborescent outgrowths of fibrovascular stroma. "In the papillomas harvested at 18 weeks, we observed that the range of Meis1-EGFP expression expanded beyond the basal layer cells of the epidermis." (PMID 25013928, 2014). "Our investigations of Meis1 in tumorigenesis indicate that, in addition to the role in papilloma development, Meis1 also functions to support the malignant conversion of benign papillomas into malignant tumors." (PMID 25013928, 2014). "Meanwhile, the observed increase in Meis1 expression in early and late papillomas suggests that the decrease in papilloma in the “after-DMBA” mice was due to Meis1’s function in papilloma maintenance." (PMID 25013928, 2014). "Taken together, our findings suggest that Meis1 supports both the development and the growth of papillomas by maintaining cell proliferation." (PMID 25013928, 2014). "Collectively, our results show that Meis1 has an oncogenic role in the epidermis, where it supports papilloma development and malignant conversion of skin tumors." (PMID 25013928, 2014). "To investigate further the role of Meis1 in cancer tissues, we analyzed Meis1 expression in chemically induced papillomas from Meis1-EGFP reporter mice by immunostaining." (PMID 25013928, 2014). "To investigate the mechanism by which Meis1 supports papilloma development, we analyzed the papillomas in K14CreER-Meis1fl/fl and Meis1fl/fl mice by standard histology methods." (PMID 25013928, 2014). "This is consistent with the observation that Meis1 expression increases as tumors progress from benign papillomas to malignant carcinomas." (PMID 25013928, 2014). "We observed co-expression of Meis1-EGFP and K14 in epidermal cell layers of early papillomas at 11 weeks after initiation." (PMID 25013928, 2014). "In addition, when the knockout of Meis1 was induced before DMBA tumor initiation, the number of papillomas significantly decreased." (PMID 25013928, 2014). "The cell marker expression studies in papillomas from Meis1 knockout mice indicate that Meis1 is not essential for maintaining CSCs in papillomas, as Meis1 expression in papillomas did not overlap with CSC-like markers." (PMID 25013928, 2014). "In contrast to Meis1 expression in normal epidermis, we found that Meis1-EGFP was not co-expressed with β4 integrin, CD34, or K15 in the tumor basal layers, where epidermal cancer stem cells are thought to reside in papillomas." (PMID 25013928, 2014). "Interestingly, in papillomas, we observed that instead of localizing to a stem cell compartment, Meis1-EGFP was co-expressed with K10, which is a marker for differentiated tumor cells in papillomas." (PMID 25013928, 2014).
pneumococcal pneumonia (1 paper, 2018). A febrile disease caused by STREPTOCOCCUS PNEUMONIAE. "Association tests pointed to single nucleotide polymorphism (SNP) rs201967957 (gene MEIS1; chromosome 2; p-valueIBS = 3.71 × 10−13) and rs576099063 (gene TSPAN15; chromosome 10; p-valueIBS = 2.36 × 10−8) as the best candidate variants associated to pneumococcal pneumonia." (PMID 29751582, 2018).
pneumonia (1 paper, 2018). An acute, acute and chronic, or chronic inflammation focally or diffusely affecting the lung parenchyma, caused by an infection in one or both of the lungs (by bacteria, viruses, fungi, or mycoplasma.). "By analyzing various transcriptomic data repositories, we found strong supportive evidence for the role of MEIS1, TSPAN15 and APOBR (encoding the receptor of the APOB protein) in pneumonia in mouse and human models." (PMID 29751582, 2018). "The gene MEIS1 was found to be down-regulated in both corneal tissue from humans (GSE58291) and lung tissue from mice (GSE45644) suffering pneumonia caused by S. pneumoniae." (PMID 29751582, 2018).
renal cell carcinoma (1 paper, 2020). "Overexpression of Meis1 inhibits renal cell carcinoma cell proliferation." (PMID 33402862, 2020).
renal fibrosis (1 paper, 2024). A final common manifestation of a wide variety of chronic kidney diseases characterized by glomerulosclerosis and tubulointerstitial fibrosis. "It is acknowledged that renal fibrosis can also be indirectly caused by the injury of renal tubular epithelial cells, and the expression of Meis1 in renal tubules was also increased." (PMID 39162106, 2024). "Mechanistically, Meis1 targets protein tyrosine phosphatase receptor J (Ptprj) to block renal fibrosis by inhibiting the proliferation and activation of fibroblasts." (PMID 39162106, 2024). "Considering the necessity of Meis1 expression in the interstitium during renal development and the importance of fibroblasts in the occurrence and development of renal fibrosis, we generated fibroblast‐specific Meis1 conditional knock‐in (Meis1‐cKI) mice." (PMID 39162106, 2024). "Fibroblast‐specific knock‐in of Meis1 inhibits myofibroblast activation and attenuates renal fibrosis and kidney dysfunction in CKD models." (PMID 39162106, 2024). "Overexpression of Meis1 in fibroblasts alleviates renal fibrosis by targeting protein tyrosine phosphatase receptor J (Ptprj) to inhibit fibroblast proliferation and activation." (PMID 39162106, 2024). "By employing bioinformatics, improved biochemical methods, and advanced genetic engineering tools, our research group has demonstrated that Meis1 was able to attenuate renal fibrosis by regulating Ptprj/PDGFRβ pathway to inhibit fibroblast proliferation and activation." (PMID 39162106, 2024). "Exogenous overexpression of Meis1 through high‐pressure injection of the plasmid in the tail vein also showed that enhanced Meis1 could improve renal fibrosis induced by UUO or UIRI." (PMID 39162106, 2024). "Our findings suggested that Meis1 could transcriptionally regulate Ptprj to alleviate renal fibrosis." (PMID 39162106, 2024). "In the current study, we confirmed the up‐regulation of Meis1 expression in renal fibroblasts clearly delayed the progression of renal fibrosis and did so by regulating Ptprj to inhibit fibroblast proliferation and activation, which retarded the malignant development of CKD." (PMID 39162106, 2024). "Taken together, Meis1 is likely to activate Ptprj through transcriptional activation and promote its expression, thereby reducing TGF‐β1‐induced cell damage and attenuating renal fibrosis." (PMID 39162106, 2024). "Accordingly, it is not difficult to speculate that Meis1‐control of Ptprj may be an important component of renal fibrosis, an aspect that has not been previously appreciated." (PMID 39162106, 2024).
skin tumor (1 paper, 2014). "The semi-quantitative RT-PCR study showed that Meis1 mRNA expression level increased during skin tumor development and progression." (PMID 25013928, 2014). "Although tumor-forming potential appears to be maintained in carcinoma stem cells of skin tumors, such an explanation for the role of Meis1 in tumorigenesis is inconsistent with our findings." (PMID 25013928, 2014). "Our observations indicate that Meis1-EGFP expression successively increases from the basal cell layer to the entire tumor as skin tumor development progresses." (PMID 25013928, 2014). "Additionally, we present RT-PCR and RNA sequencing data that show that Meis1 expression is successively enhanced with skin tumor progression." (PMID 25013928, 2014). "Taken together, these results indicate that the successive increase of Meis1 expression during skin tumor development is not due to the increase in mesenchymal tissue associated with EMT, but rather indicates oncogenic potential of Meis1 during tumorigenesis." (PMID 25013928, 2014).
spindle cell sarcoma (1 paper, 2024). A malignant mesenchymal neoplasm composed of spindle-shaped cells. "Taken together, the imaging, histologic, immunohistochemical, and molecular findings led to a diagnosis of a primary lung low-grade undifferentiated spindle cell sarcoma with MEIS1::NCOA2 fusion." (PMID 38678288, 2024). "Ultimately, given a completely negative metastatic workup, a diagnosis of lung primary low-grade undifferentiated spindle cell sarcoma with MEIS1::NCOA2 fusion was rendered." (PMID 38678288, 2024).
thymic atrophy (1 paper, 2014). "Further studies on the function of Meis1 in TECs, in relation to the p63-FoxN1 regulatory axis, could provide an avenue for clarifying the molecular mechanism underlying age-associated thymic atrophy." (PMID 24594519, 2014).
Ureteral obstruction (1 paper, 2024). Obstruction of the flow of urine through the ureter. "We then evaluated the renal expression of Meis1 using two CKD mouse models, a unilateral ureteral obstruction (UUO) model and a unilateral ischemia/reperfusion injury (UIRI) model." (PMID 39162106, 2024).
urothelial cell carcinoma (1 paper, 2020). "On the other hand, Meis1 methylation analysis of patient urine samples of painless hematuria also showed that Meis1 was a significant predictor for the presence of urothelial cell carcinoma." (PMID 33402862, 2020).
Ventricular arrhythmia (1 paper, 2024). "Meis1 overexpression was found to reduce ventricular arrhythmias and improve cardiac conduction velocity, partly by restoring the function of cardiac Na+ channels." (PMID 39758840, 2024).
Visual impairment (1 paper, 2016). "It was recently shown that Meis1 regulates either directly or indirectly the expression of genes involved in patterning, proliferation and differentiation of the neural retina, and that haploinsufficiency of Meis1 causes micropthalmic traits and visual impairment in adult mice." (PMID 27918583, 2016).
cancer (72 papers, 2010 to 2026). A tumor composed of atypical neoplastic, often pleomorphic cells that invade other tissues. "Upregulation of MEIS1 in cancers such as breast, colorectal, oesophageal, neuroblastoma, ovarian and prostate has been observed to be associated with increased cancer aetiology and progression." (PMID 41535654, 2026). "Proteoglycans in cancer is the most enriched pathway associated with MEIS1 and HOXB13 inhibition, inducing tumor suppression and DCN, LUM, and TGFBR3, as well as regulating growth factor, migration, and invasion signaling through receptor tyrosine kinases." (PMID 36661515, 2023). "Multiple enriched genes (Hoxa6, Hoxa10, and Meis1) in the pathway of transcriptional misregulation in cancer were associated with LSC self-renewal and survival." (PMID 36593968, 2023). "Collectively, our findings suggest MEIS1 as a potential target gene of ICG-001 treatment associated with cancer stemness and CRC malignancy." (PMID 34948208, 2021). "Deregulation of Hox protein cofactors MEIS2, MEIS1 and Pbx1 are associated with cancer oncogenesis and tumor progression." (PMID 24391925, 2013). "Similarly, we observed an association of HOXA9 with PBX1, PBX2, PBX3, and MEIS1 in all 10 cancer types except for STAD." (PMID 38904676, 2024). "Therefore, it is possible that the hemimethylation of hub genes like MEIS1 affects protein, biochemical, or regulatory functions of genes that are associated with cancer." (PMID 33711952, 2021). "Down-regulation of these inhibitors often associates with poor prognosis of human cancers, thus it is valuable to further study whether MEIS1 regulates expression of CDK inhibitors in the future." (PMID 28270206, 2017). "Why does overexpression of Meis1 cause cancer and how does Prep1 inhibit?" (PMID 26259236, 2015). "The results showed that ENL cancer mutants form prominent condensates, primarily at Hoxa cluster genes and Meis1." (PMID 39327672, 2025). "By inhibiting the formation of ENL condensates at target genes (Hoxa cluster and Meis1 gene) with small‐molecule TDI‐11055, the gene dysregulation and cancer development caused by ENL mutations got effectively repressed." (PMID 39327672, 2025). "The results showed that the expression levels of DNM1, MEIS1, and SUSD3 were associated with many cancer immune checkpoints." (PMID 38167056, 2024). "Additionally, MEIS1 was also downregulated in a variety of tumors, where downregulation was linked to the immune infiltration level of cancer patients and low expression predicted poor overall survival in kidney renal clear cell carcinoma and various other cancers." (PMID 38347632, 2024). "Analysis of the HOXA9 gene revealed a positive correlation with PBX1, PBX2, PBX3, and MEIS1 in all cancer types except for STAD among the 11 studied genes, suggesting enhanced binding of HOXA9 to the promoter region of target genes." (PMID 38904676, 2024). "The results of the pan-cancer analysis showed that MEIS1 and DNM1 were significantly highly expressed in AML; MEIS1 and SUSD3 are potential risk factors for the prognosis of AML, and DNM1 is a potential protective factor." (PMID 38167056, 2024). "We indicated that MEIS1 can play a role in the growth and progression of cancer and have a close correlation with immune regulation." (PMID 36836180, 2023). "The TMB, MSI, and NEO which characterize anti-tumor immunity were negatively related to MEIS1 expression in some cancers." (PMID 36836180, 2023). "The 33 cancer types were studied to identify MEIS1 expression in this study and it finally suggests that MEIS1 expression is different between tumor tissues and normal tissues in 23 cancer types." (PMID 36836180, 2023). "In our study, we comprehensively performed MEIS1 expression and its correlation with prognostic and immunotherapy value in pan-cancer via different databases." (PMID 36836180, 2023). "Among these 23 cancer types, MEIS1 expression is down-regulated in 18 cancer types, on the contrary, the other 5 types were up-regulated." (PMID 36836180, 2023).